TSC1 (TSC complex subunit 1)
Diseases named in the same sentence as TSC1 in open-access papers (continued):
Sharing a sentence is not in itself a finding about the gene and the disease.
renal cell carcinoma (23 papers, 2009 to 2025). "Alterations in TSC1 gene were noted in three patients: a patient with anaplastic thyroid cancer who harbored a nonsense mutation in TSC1 (p.Trp103*) and a renal cell carcinoma patient with a TSC1 splicing variant (c.1029+1G>A)." (PMID 26859683, 2016). "In one of these three possible renal cell carcinomas (case P0039), copy loss of TSC1 and a likely loss-of-function deletion in NF2 were detected, strongly suggesting AKT/mTOR pathway was activated." (PMID 27245685, 2016). "For example, we and others have shown that mTOR inhibition attenuates chemotherapy-mediated cell death in colon and renal cell carcinoma cell lines, and in certain genetic contexts, such as loss of TSC1/2 or REDD1." (PMID 25460505, 2015). "Tfe3-gene fusions can be causal for renal cell carcinomas, which also occur in tuberosclerosis due to mutations in Tsc1 or Tsc2 and in Bird-Hogg-Dubé (BHD) syndrome due to Flcn mutations." (PMID 23582324, 2013). "Studies in patients with renal cell carcinoma have shown that mutations in TSC1/2 and mTOR are associated with rapalog resistance, although these mutations are not present in most patients, supporting the potential of targeting Ephexin1 in overcoming resistance." (PMID 40855114, 2025). "Therefore, we can conclude that there is a strong association between ESC-RCC and the presence of TSC1/2 gene mutations, even though the molecular characteristics of this particular type of renal cell carcinoma require further investigation." (PMID 38892169, 2024). "The mTOR pathway was considered to play a central role in cell growth and metabolism regulating in renal cell carcinomas oncogenesis and the activation of mTOR results in the downregulation of fumarase and fumarate accumulation in Tsc1-deficient animals and cells." (PMID 35163394, 2022). "Given that heterozygous loss of TSC1 is common in renal cell carcinoma (>30%), TSC1 and TSC2 may be screened as predictive biomarkers of everolimus in renal cell carcinoma patients who progressed on VEGF-targeted therapy." (PMID 26859683, 2016). "Similarly, we identified 1 TSC1 splicing variant (renal cell carcinoma), 1 TSC1 nonsense mutation (anaplastic thyroid cancer), 1 TSC1 missense mutation (sarcoma) and 1 TSC2 missense mutation (angiosarcoma)." (PMID 26859683, 2016). "Genes implicated in renal cell carcinoma development—VHL, TSC1/2, and FLCN—will be used as examples to explore this concept, as well as how pathogenic mutations of tumor suppressors cause disease by disrupting protein chaperoning, maturation, and function." (PMID 39352796, 2024). "There was a recent report of renal cell carcinoma patients with extended benefit from mTOR inhibitor showed that TSC1 and TSC2 offer explanation for treatment response." (PMID 26859683, 2016). "An additional two had no associated tumor but a family history of such tumors in a first-degree relative (colorectal cancer at age 56 years for the individual with a SMAD4 translocation and renal cell carcinoma at age 69 for the individual with the TSC1 duplication)." (PMID 29909963, 2018). "Genes showing a 2-fold overexpression in both the benign oncocytoma-like regions and high-grade oncocytic carcinoma regions included several notable genes such as VHL, HIF1A (hypoxia inducible factor 1), cMET, and TSC1 (tuberous sclerosis 1), which are cancer genes involved in renal cell carcinoma." (PMID 25275525, 2014). "Genomic studies identifying the genes for kidney cancer, including the VHL, PBRM1, MET, FLCN, fumarate hydratase, succinate dehydrogenase, TSC1, TSC2, and TFE3 genes are known to play role in renal cell carcinoma development." (PMID 35709632, 2022).
renal cell carcinoma (continued). "Loss of heterozygosity (LOH) at the TSC1 or TSC2 loci has been detected in TSC-associated hamartomas and renal cell carcinoma (RCC) as well as in sporadic tumors of non-TSC patients." (PMID 19265534, 2009).
Intellectual disability (22 papers, 2013 to 2025). "Mutational variants identified in the TSC2 gene correlated with a more severe clinical presentation, including severe intellectual disability and treatment-resistant seizures, compared to variants in the TSC1 gene." (PMID 40364023, 2025). "Patients with TSC2 mutations had more severe seizures, were diagnosed 9–11 years earlier and were significantly more likely to have intellectual disabilities than those with TSC1 mutations." (PMID 41291828, 2025). "Patients with TSC2 variants usually present a higher number of tubers, an earlier age of seizure onset, and a higher prevalence of intellectual disability compared to those with TSC1 variants." (PMID 38439608, 2024). "Tuberous sclerosis complex (TSC), a developmental disorder characterized by intellectual disability, epilepsy, and the presence of cortical tubers, arises from mutations that inhibit the function of the Tsc1 and Tsc2 genes." (PMID 38455054, 2024). "We did not observe gene expression differences between important subgroups, that is individuals with TSC2 versus TSC1 mutations, or mild versus severe intellectual disability." (PMID 28808237, 2017). "However, evidence from the literature suggests that TSC2 mutations are associated with a higher proportion of severe phenotypes, developmental deficits, and intellectual disability than TSC1 mutations." (PMID 37946245, 2023). "However, another study revealed that only milder developmental delay and/or intellectual disability was observed in patients with TSC1 mutations than in those with TSC2." (PMID 33679864, 2020). "Therefore, TSC1 is the first promising intervention to alleviate perinatal white matter loss and to prevent long-term disabilities, such as cerebral palsy and intellectual disabilities." (PMID 24961618, 2013). "Therefore, it is unknown what kind of TAND symptoms patients without intellectual disabilities have, and whether there are any differences between TSC1 and TSC2 patients." (PMID 36232477, 2022).
fragile X syndrome (19 papers, 2013 to 2024). A genetic syndrome caused by mutations in the FMR1 gene which is responsible for the expression of the fragile X mental retardation 1 protein. "Deregulation of mTOR signaling has been identified as a phenotypic feature common to various forms of ASD, including fragile X syndrome, and mutations in tuberous sclerosis complex 1 and 2 (TSC1/2), neurofibromatosis 1, and phosphatase and tensin homolog (PTEN)." (PMID 30020076, 2018). "Common examples are fragile X syndrome (FXS) caused by a mutation in the FMR1 gene and tuberous sclerosis complex (TSC) caused by a mutation in TSC1 and TSC2 genes." (PMID 33450950, 2021). "The mTOR signaling pathway is a convergent pathway that is disturbed by genetic variations in the TSC1 and TSC2 (TSC), PTEN (Bannayan-Riley-Ruvalcaba syndrome, Lhermite-Duclos syndrome, and Cowden syndrome), FMRP (fragile X syndrome), and NF1 (neurofibromatosis type 1) genes." (PMID 36732866, 2023). "Furthermore, in addition to the genetic defect in Tsc1/2 and Pten, the lack of FMR1 expression, which leads to fragile X syndrome (FXS), an autism-associated disorder, also demonstrated hyperactive mTOR signaling both in KO mice and in FXS patients." (PMID 31849609, 2019).
renal angiomyolipomas (19 papers, 2011 to 2026). "Like kidney cysts, the hazard of having kidney angiomyolipomas was over twice higher in patients with TSC2 mutation than in those with TSC1 mutation (p = 0.029)." (PMID 38483608, 2024). "Misappropriation of Tsc1 destabilized the Tsc1-dependent tumor suppressor Tsc2 and led to the development of a renal angiomyolipoma, a tumor subtype more commonly associated with Tsc1/2 inactivating mutations." (PMID 35070081, 2022). "First, a patient-derived cell line LAM-621 (LAM-associated renal angiomyolipoma) harboring a variant in TSC2 (p.Arg611Gln) rendering it unable to complex with TSC1, resulting in hyperactivated mTORC1 signaling." (PMID 34162842, 2021). "TFEB is also primarily nuclear in TSC-associated RCC and renal angiomyolipomas, and in Tsc1/2-null MEFs." (PMID 34253722, 2021). "Similar to the overall sample, renal angiomyolipomas were asymptomatic in most patients with TSC1 (90.2%) and TSC2 (83.1%) mutations." (PMID 33041968, 2020). "Patients with TSC2 mutations were reported to exhibit a higher incidence and severity of both renal angiomyolipoma and cysts than those with TSC1 mutations." (PMID 33041968, 2020). "Furthermore, more patients with TSC2 mutations received intervention for renal angiomyolipoma than those with TSC1 mutations." (PMID 33041968, 2020). "The germline mutation of the TSC1/2 gene in bilateral renal angiomyolipomas is unclear." (PMID 31927531, 2020). "Mutation studies have shown the occurrence and severity of TSC-associated renal angiomyolipomas and cysts to be higher among patients with TSC2 mutation than those with TSC1 mutation." (PMID 33041968, 2020). "We found that cardiac rhabdomyomas and renal angiomyolipomas were more common in patients with a PV in TSC2 than in TSC1 (7:1 and 4:1, respectively); in this, our results are similar to those of other published studies." (PMID 32313033, 2020). "Our results indicate that genetic alterations in TSC2/TSC1 are the primary and essential driver genetic events for development and progression of renal angiomyolipoma." (PMID 27494029, 2016). "Specifically, there is a fourfold increase in lung cysts (χ2 = 4.14 p = 0.04), a twofold increase in renal angiomyolipomas (χ2 = 14.14 p < 0.001), and a fivefold increase in liver angiomyolipomas (χ2 = 6.96 p = 0.008) if the patient has a TSC2 mutation compared to TSC1 mutation." (PMID 35292049, 2022). "The mean age at diagnosis of renal angiomyolipomas was 13.3 years (median, 9 years, range <1–59 years) in patients with a TSC2 mutations, while it was 22.5 years (median 21 years, range <1–60 years) in those with a TSC1 mutations." (PMID 33041968, 2020). "We conclude that sporadic renal angiomyolipoma usually have mutations in TSC2, but not TSC1 or RHEB, and have no other common genomic events, among those we searched for." (PMID 21949787, 2011).
cyst (17 papers, 2008 to 2024). A sac-like closed membranous structure that may be empty or contain fluid or amorphous material. "Histopathology analysis indicated a significant reduction in cyst overload in kidneys obtained from Tsc1 KO mice fed an arginine-deficient diet." (PMID 37290438, 2023). "Ablation of Tsc1 in these cells causes cyst from loop of Henle, which is different from the cyst caused by ablation of Tsc1 in Osx-labeled tubular cells in morphology and origin." (PMID 30696882, 2019). "Lessened GTP levels in the Tsc1 KO kidneys can also be caused by its increased consumption during aminoacyl t-RNA formation and enhanced protein synthesis both of which are necessary for cell proliferation and important to cyst formation and growth in TSC." (PMID 36142537, 2022). "The deletion of Foxi1, a protein that is vital to H+-ATPase expression and IC cell viability, completely inhibited mTORC1 activation and abrogated the cyst burden in 47-day-old Tsc1/Foxi1 dKO mice." (PMID 38731991, 2024). "The magnitude of cyst burden in Tsc1/Car2 dKO mice correlated with the expression levels of Foxi1 and was proportional to mTORC1 activation." (PMID 38731991, 2024). "The most cogent point of these results is the progressive increase in the expression of A-IC cell-specific genes in the kidneys of Tsc1/Car2 dKO mice, as their cyst burden increases over time (day 47 vs. day 110 samples)." (PMID 38731991, 2024). "The Tsc1/Car2 dKO mice displayed significant cyst burden at 110 days of age when compared to 47-day-old Tsc1 KO mice." (PMID 38731991, 2024). "Inactivation of carbonic anhydrase 2 (Car2) significantly reduced, whereas, deletion of Foxi1 completely abrogated the cyst burden in Tsc1 KO mice." (PMID 38731991, 2024). "In these studies, we contrasted the ontogeny of cyst burden in Tsc1/Car2 dKO mice vs. Tsc1/Foxi1 dKO mice." (PMID 38731991, 2024). "Nevertheless, TSC1 demonstrated better cyst-free survival (median 16.9 years) than TSC2 (median 9.1 years) at any time." (PMID 38832977, 2024). "The majority of AML/cyst-positive patients had a TSC2 mutation (51.7%), with only 10.8% having a TSC1 mutation." (PMID 39027368, 2024). "Deletion of FOXI1, which is vital to H+-ATPase expression and intercalated (IC) cell viability, completely inhibited mTORC1 activation and abrogated the cyst burden in the kidneys of Tsc1 KO mice." (PMID 38028758, 2023). "For example, embryonic Tsc1 KO mice with Nse-Cre had earlier cyst formation in the proximal nephrons starting at P712." (PMID 36627370, 2023). "In Cd79a-Tsc1 KO kidneys at 4 weeks of age, very few apoptotic nuclei were seen in the cyst lining and interstitium." (PMID 36627370, 2023). "In contrast, postnatal Tsc1 KO mice with Aqp2-Cre exhibited later cyst progression after 4 to 8 weeks of age." (PMID 36627370, 2023). "This mosaic feature of cyst-lining cells is in agreement with previous rodent models of Tsc1 and PKD1/2 inactivation." (PMID 36627370, 2023). "Further study is necessary to examine the detailed analysis of B cell behaviors in the Cd79a-Tsc1 KO kidney and to trace the changes until the later stage of cyst formation." (PMID 36627370, 2023). "Deletion of FOXI1, which is vital to H+-ATPase expression and IC cell development, completely inhibited mTOR activation and abrogated the cyst burden in Tsc1 KO mice." (PMID 38028758, 2023). "To confirm that Tsc1 and gig mutant clones were lost to differentiation, we stained these clones with antibodies against Zfh1 and Eya, to mark CySCs and differentiated cyst cells." (PMID 34898607, 2021). "While control clones were composed of both Zfh1-expressing CySCs and Eya-positive cyst cells (arrowheads and arrows, respectively), Tsc1 and gig homozygous mutant clones consisted mostly of Eya-positive cells (arrows)." (PMID 34898607, 2021). "Since Osx labels tubular cells, these results suggest that Tsc1 deletion in tubular cells leads to cyst formation." (PMID 30696882, 2019).
cyst (continued). "Inhibition of glutamine metabolism in both Lkb1/Tsc1 and Pkd1 mutant mice significantly reduces cyst progression." (PMID 29483507, 2018). "Moreover, ASS1 immunostaining of mouse kidney samples indicated high expression in Tsc1 KO kidneys, specifically in cyst-lining epithelial cells." (PMID 37290438, 2023). "In Cd79a-Tsc1 KO kidneys, cilia are elongated in distal tubule cells at P9 before cysts overtly arise, suggesting that cilia length defects may contribute to cyst initiation." (PMID 36627370, 2023). "A subsequent study showed that glutamine-dependence caused by ablation of Lkb1 in combination with ablation of Tsc1 gene resulted in very aggressive cystogenesis in a mouse model and inhibition of glutamine metabolism in both Lkb1/Tsc1 and Pkd1 mutant mice significantly reduced cyst progression." (PMID 32847032, 2020). "As previously reported, Tsc1 deletion resulted in kidney overgrowth and cyst formation." (PMID 32581239, 2020). "We reasoned that if downregulation of PC-1 is involved in cyst formation, lowering the starting amount of PC-1 might enhance the phenotype in Tsc1 mutants." (PMID 26931735, 2016). "A role for haploinsufficiency in Tsc1 in cyst formation was proposed." (PMID 23105973, 2012). "In contrast, in Cd79a-Tsc1 KO mice, pre-cystic tubule cells around P11 showed both distorted CE and OCD and cilia elongation, all of which preceded overt cyst appearance." (PMID 36627370, 2023). "In contrast, the Tsc1/Foxi1 dKO mice displayed a complete absence of cyst formation at both 47 and 110 days of age." (PMID 38731991, 2024). "The life span of Tsc1 KO mice, which is less than 60 days, did not allow for direct comparison of cyst burden to that of 110-day-old Tsc1/Car2 dKO mice." (PMID 38731991, 2024). "mTORC1 was activated in a portion of cyst-lining cells and occasionally even when Tsc1 was not depleted, implying a non-autonomous mechanism." (PMID 36627370, 2023). "Furthermore, we demonstrated that metformin did not prevent cyst formation in tsc1a morphants resulting from knocking down the AMPK downstream target TSC1." (PMID 28769124, 2017).
autism spectrum disorder (14 papers, 2009 to 2023). A spectrum of developmental disorders that includes autism, and Asperger syndrome. "Tuberous sclerosis complex related genes such as Tsc1 and Tsc2, which are upstream modulators of mTOR, are also associated with autism spectrum disorder and epilepsy." (PMID 32424120, 2020). "For instance, mutations in the TSC1 or TSC2 genes cause tuberous sclerosis complex (TSC) in humans, a neurogenetic condition associated with autism spectrum disorder, epilepsy, and intellectual disability." (PMID 35840801, 2023). "Mutations in the human TSC1 and TSC2 genes are often attended with comorbid phenotypes associated with autism spectrum disorders (ASDs)." (PMID 35857265, 2022). "Tuberous sclerosis complex (TSC), a multi-system genetic disorder often associated with autism spectrum disorder (ASD), is caused by mutations of TSC1 or TSC2, which lead to constitutive overactivation of mammalian target of rapamycin (mTOR)." (PMID 33863288, 2021). "It is also unclear whether the pathway network also plays a critical role in impaired social behaviors in autism spectrum disorders not caused by Tsc1 and Tsc2 mutations." (PMID 36732866, 2023). "It is unclear whether the signaling pathway also plays a critical role in autism spectrum disorders not caused by Tsc1 and Tsc2 mutations." (PMID 36732866, 2023). "Tuberous sclerosis complex (TSC) is an inherited neurocutaneous disorder caused by mutations in TSC1 or TSC2 genes, with patients often exhibiting neurodevelopmental (ND) manifestations termed TSC-associated neuropsychiatric disorders (TAND) including autism spectrum disorder (ASD)." (PMID 37034588, 2023). "TSC1 and TSC2 are tumor suppressor genes that are mutated in the autosomal dominant tumor syndrome tuberous sclerosis complex (TSC), which is characterized by widespread benign tumors and a high incidence of epilepsy, autism spectrum disorders, and cognitive deficits." (PMID 19593385, 2009). "Specifically, rpS6, p-eIF4E, TSC1 and p-MNK1 expression discriminated patients according to their clinical diagnosis, suggesting that components of protein synthesis signalling pathways might constitute a molecular signature of clinical severity in autism spectrum disorder." (PMID 30705255, 2019).